LINC02245 (long independently transcribed non-coding RNA 2245)
Synonyms: lnc-SERTAD2-3; AC007386.2
Gene: Long non-coding RNA gene on chromosome 2 (64,901,840 to 65,056,233, reverse strand). Ensembl gene ENSG00000237638.
Gene Ontology:
Biological process: SRP-dependent cotranslational protein targeting to membrane, signal sequence recognition
Cellular component: signal recognition particle, endoplasmic reticulum targeting